WFS1 (wolframin ER transmembrane glycoprotein)
Diseases named in the same sentence as WFS1 in open-access papers (continued):
Sharing a sentence is not in itself a finding about the gene and the disease.
diabetes (continued). "Together with the WFS1 study, our results have a number of implications for the study of rarer genetic variation in diabetes." (PMID 21569088, 2011). "A recent study demonstrated that liraglutide treatment reversed unconventional cellular defects in WFS1-mutant β-cells, suggesting that repurposing existing diabetes drugs could offer a disease-modifying strategy for this orphan disease." (PMID 41614934, 2026). "The WFS1 gene has also been recognized as a Maturity‐Onset Diabetes of the Young (MODY) gene." (PMID 40641032, 2025). "Moreover, WFS1 is likely to be involved also in type 2 diabetes mellitus (T2DM), as islets from T2DM donors had significantly lower levels of WFS1 and insulin gene expression than islets from donors without diabetes." (PMID 40988749, 2025). "Notably, we identified a CISD2 peptide that alleviates ER calcium defects of WFS1- or CISD2-deficient cells by solely increasing IP3R activity, further showing that this peptide mitigates diabetes-like phenotypes as well." (PMID 40181095, 2025). "Therefore, by utilizing the Comparative Toxicogenomics Database (CTD), GeneCards, and Gene Set Enrichment Analysis (GSEA) databases, we successfully identified the WFS1 gene, a crucial player in both EC and diabetes." (PMID 39478865, 2024). "The WFS1 gene is associated with diverse phenotypes, ranging from nonsyndromic diabetes to syndromic conditions." (PMID 39221226, 2024). "WFS1 heterozygous variants have been reported to cause DFNA6/14/38 and wolfram-like syndrome, which is characterized by autosomal dominant nonsyndromic hearing loss (ADNSHL), optic atrophy and diabetes mellitus." (PMID 37041640, 2023). "To assess whether dulaglutide could indeed reverse impaired glucose tolerance or diabetes, we treated 7- and 20-week-old Wfs1 KO mice for 4–12 weeks." (PMID 36995380, 2023). "To investigate the features of isolated diabetes (without OA, DI, or D) caused by WFS1 variations, we reviewed the published literature and selected 51 patients from 13 studies." (PMID 37277527, 2023). "Thus, the phenotypes of WFS1-related diabetes are sometimes atypical and often misdiagnosed as type 1 diabetes, type 2 diabetes, or MODY." (PMID 37277527, 2023). "More recently, some case reports or case series have been published, detailing non-syndromic and non-autoimmune insulin-dependent forms of diabetes due to the WFS1 mutations." (PMID 36294752, 2022). "As the patient has not developed diabetes mellitus and only one mutated allele was found in WFS1, the patient was diagnosed with Wolfram-like syndrome, according to the available guidelines." (PMID 36330437, 2022). "The presence of deafness and diabetes in the maternal aunts led to the discovery of a WFS-1 mutation in the maternal pedigree, although none of the members had diabetes." (PMID 34630320, 2021). "Whether liraglutide prevents or only delays diabetes in Wfs1 KO rats is still unknown, thus the aim of this study was to investigate if long-term, preventive treatment, was able to stop the development of diabetes." (PMID 34831417, 2021). "Thus, we can conclude that liraglutide treatment was able to prevent the onset of diabetes in 55% Wfs1 KO animals and delay the onset of diabetes in 45% Wfs1 KO animals." (PMID 34831417, 2021). "The third patient (Proband No. 3) had two WFS1 disease-causing variants but had only optic atrophy without diabetes or hearing loss." (PMID 34573359, 2021). "WFS1 also causes autosomal dominant (AD) nonsyndromic progressive low-frequency SNHI and AD Wolfram-like syndrome (WFSL; OMIM: 614296) that is characterized by congenital progressive low- and middle-frequency SNHI, diabetes mellitus, and optic atrophy." (PMID 33879837, 2021). "These two cases support recent findings that biallelic heterozygous or homozygous WFS1 variants can be associated with nonsyndromic or syndromic autosomal recessive OA without diabetes or hearing loss." (PMID 31765440, 2019).
diabetes (continued). "The aim was to investigate whether chronic treatment with the GLP-1 receptor agonist liraglutide, starting before the onset of metabolic symptoms, would be able to prevent or delay the development of diabetes in Wfs1 KO rats." (PMID 29976929, 2018). "Homozygous or compound heterozygous mutations in WFS1 cause WS, which is characterized by a lack of insulin secretion leading to diabetes mellitus, optic atrophy, and several other phenotypes." (PMID 29207974, 2017). "Further studies are needed to verify the functional interaction between WFS1 and TRPM5 in the regulation of insulin secretion and how this downregulation may contribute to diabetes‐like phenotype of WFS1‐deficient mice." (PMID 27053292, 2016). "Among genetic variants, the diabetes-associated variants in TCF7L2 (rs7903146) and WFS1 (rs10010131) have been shown to affect the response to exogenous GLP-1, while variants in KCNQ1 (rs151290, rs2237892, and rs2237895) have been reported to alter endogenous GLP-1 secretion." (PMID 25785276, 2015). "Taking these data together, interaction of miRNAs and WFS1 could be of great importance in the molecular background of diabetes mellitus." (PMID 26426397, 2015). "Comparison of ages at onset of diabetes mellitus and optic atrophy in subjects with and without a mutated WFS1 gene." (PMID 25211237, 2014). "Among the three patients with WFS1 homozygous mutation two carried inactivating and one non-activating; their mean ages at onset of diabetes were 5,5 and 10 years respectively." (PMID 22238590, 2012). "Background/Objectives: A heterozygous mutation in the WFS1 gene is responsible for autosomal dominant non-syndromic hearing loss (DFNA6/14/38) and Wolfram-like syndrome, which is characterized by bilateral sensorineural hearing loss with optic atrophy and/or diabetes mellitus." (PMID 39858604, 2025). "This study investigated the connection between diabetes and EC, with a specific focus on elucidating the biological implications of the diabetes mellitus (DM)-related gene WFS1." (PMID 39478865, 2024). "Molecular tests found a pathogenic variant in GCK gene, confirming GCK-MODY diabetes and additionally a heterozygous pathogenic variant in the GJB2 gene that identified the patient as a carrier of nonsyndromic hearing loss, and a heterozygous variant in the WFS1 gene (c.68C>T)." (PMID 39766859, 2024). "No studies have been pubished reporting whether isolated diabetes caused by WFS1 mutations develops into the syndrome; however, further follow-up is necessary." (PMID 37277527, 2023). "In addition to NKX6–1 we found variants in WFS1, RFX6 and 7 other genes associated with monogenic forms of diabetes (AKT2, EIF2AK3, GLIS3, HADH, MNX1, NKX2–2, and PTF1A) and they may be relevant to development of MODY." (PMID 29439679, 2018). "The WFS1 gene is one of the genes repeatedly shown to be associated with Type 2 diabetes, indicating that WFS may be an unusual example of a Type 2-like diabetes mellitus of monogenic cause." (PMID 23981289, 2013). "More recently, a mutant rat line was obtained through Wfs1 exon 5 disruption showing the hallmarks of WS1, with diabetes, optic atrophy, and neurodegeneration." (PMID 36645345, 2023). "However, recent studies have shown that syndromic monogenic diabetes genes (particularly m.3243A > G, HNF1B and WFS1) are more common than previously thought and usually lack their typical syndromic clinical features, presenting overlapping diabetes phenotypes with non‐syndromic monogenic diabetes." (PMID 35822264, 2022). "Our list is supported by colocalization of genes known to lead to Mendelian forms of diabetes (e.g., SLC2A2 and WFS1) and of genes with previously demonstrated mechanisms of association with IR/T2D (e.g., METAP2, PLEKHA1 [TAPP1], FAM13A, and KLF14)." (PMID 35292083, 2022). "The SNPs in 3′UTR of miRNA target genes reported in diabetes include rs11724758 in FABP-2; rs1046322 in WFS-1; rs2229295 in HNF1B; rs1063192 in CDKN2B; and rs13702 in LPL genes." (PMID 34925466, 2021).
diabetes (continued). "In both T1D and T2D, we found enrichment of monogenic forms of diabetes, as expected —2 genes in T1D (RASGRP1, INS) and 8 in T2D (HNF1B, GCK, WFS1, KCNJ11, ABCC8, HNF1A, PPARG, SLC2A2)." (PMID 33836063, 2021). "In the last decade, there are other studies that reported genes other than known OMIM MODY genes to be involved in early onset of diabetes and MODY i.e. RFX6 and WFS1 genes." (PMID 34763692, 2021). "Candidate target genes also included six genes involved in MODY and other monogenic and syndromic forms of diabetes (ABCC8, KCNJ11, GCK, INS, GLIS3, WFS1)." (PMID 31064983, 2019). "The phenotype of Wfs1-ex5-KO232 rats indicates that it has these core symptoms of WS, including progressive insulin-dependent diabetes mellitus, retinal gliosis and cataracts, as well as displaying degeneration of the medulla and optic nerve." (PMID 28860598, 2017). "The data of Bao and our results show, that these different pathways can be in the background of the same phenotype, as miR-185 is suggested to be related to diabetes mellitus via two different (SOCS3 and WFS1) targets." (PMID 26426397, 2015). "Although she was diagnosed with diabetes at the age of 35, she had no hearing loss, optic atrophy or visual impairment, and WES showed only the WFS1 mutation c.985T>A/p.F329I." (PMID 40641032, 2025). "These experiments suggest that WFS1 and CISD2 interact independently at distinct sites on IP3R to manipulate its activity, demonstrating their roles as IP3R regulators and emphasizing ER calcium dysfunction as a major mechanism of WS-related diabetes." (PMID 40181095, 2025). "The spectrum of causative genes (PTF1A, GLIS3, WFS1, INSR, SLC29A3, ZNF808, ABCC8, INS) is markedly different from the monogenic diabetes genes seen in non-consanguineous cohorts, and also different from those seen in other consanguineous populations." (PMID 37897565, 2023). "The mouse model for the WFS1 syndrome that lacked two-thirds of the WFS1 gene reproduced all clinical features of this complex disease, like diabetes and mental disorders." (PMID 37759745, 2023). "Peripheral blood RNA sequencing results of patients and carriers suggest that WFS1 may affect immune-related pathways and the transcriptional expression of HLA-DRB1 may be related to the pathogenesis of diabetes." (PMID 36967753, 2023). "Traditionally, WFS1-related diabetes was not considered in MD genetic screening panels as they were usually based only on MODY genes." (PMID 36294752, 2022). "Female Wfs1-ex5-KO232 rats develop diabetes mellitus later, at approximately at 14–16 months of age (data not shown)." (PMID 28860598, 2017). "The associations of 23 SNPs located within 17 candidate genes (MTHFR, PPARγ, LPL, INSIG, TCF7L2, FTO, KCNJ11, JAZF1, CDKN2A/B, ADIPOQ, WFS1, CDKAL1, IGF2BP2, KCNQ1, MTNR1B, IRS1, ACE) with overweight and obesity, diabetes, metabolic phenotypes, and MetS were examined in both studies." (PMID 24959828, 2014). "Thus, we can conclude that liraglutide treatment delays but does not prevent the development of diabetes in Wfs1 KO rats." (PMID 34831417, 2021). "However, Wfs1 mutant mice do not develop diabetes to the same extent as human patients with WS." (PMID 28860598, 2017). "Eight (38%) individuals (GCK [four], WFS1 [two], HNF1B [one] and LMNA [one]) had been diagnosed with monogenic diabetes during their clinical follow-up, irrespective of our study." (PMID 36418577, 2023).
optic atrophy (75 papers, 2007 to 2026). A disorder characterized by loss of optic nerve fibers. "Sensory: WFS1 is linked to optic atrophy and deafness; GLIS3 to congenital glaucoma; PAX6 to aniridia." (PMID 41614934, 2026). "In particular, heterozygous mutations in the WFS1 gene have been linked to isolated adult-onset diabetes with low penetrance for WS features such as optic atrophy, hearing impairment, and isolated congenital nuclear cataract." (PMID 41614819, 2025). "Sometimes it is also associated with congenital nuclear cataract-41, with recent studies showing that certain pathogenic variants of the WFS1 gene are associated with non-syndromic optic atrophy." (PMID 39064493, 2024). "Recently, the coexistence of optic atrophy and hearing loss was described to be common phenotype in patients with heterozygous WFS1 variants." (PMID 39766859, 2024). "For children with insulin-dependent diabetes and optic atrophy, WFS1 pathogenic variants need to be further excluded; exome sequencing is helpful for the diagnosis of this disease." (PMID 36967753, 2023). "The causative variants in PTPN23, TMEM126A, NBAS, and WFS1 genes were identified in 4 probands with a recessive form of optic atrophy." (PMID 36071901, 2022). "This variant has been identified as a hotspot of WFS1-related disorder with combined optic atrophy and deafness." (PMID 34573359, 2021). "Patient # 8 presented with asymptomatic optic atrophy (correctable vision loss) and was identified to have a pathogenic variant (WFS1 c.1941C>A; p.Cys647) and a VUS (c.1597C>T; p.Pro533Ser) in trans." (PMID 31765440, 2019). "Nevertheless, optic atrophy associated with the WFS1 gene p.A684V variant may be late onset, and ophthalmologic follow-up is necessary in the consideration of the possibility of late onset optic atrophy." (PMID 39858604, 2025). "Mutations in WFS1 are well known to cause autosomal-recessive Wolfram syndrome, a severe neurodegenerative disease mainly characterized by juvenile-onset diabetes mellitus and optic atrophy (OMIM 222300)." (PMID 36843716, 2023). "The genetic study of her DNA using a custom-designed next-generation sequencing (NGS) panel detected a de novo pathogenic heterozygous variant in the WFS1 gene related to Wolfram-like syndrome, which is characterized by the presence of other symptoms such as optic atrophy." (PMID 36330437, 2022). "Finally, 12 patients with late-onset WS (LOWFS) developed DM and optic atrophy at 15 years of age or later and they carried at least one WFS1 mutation." (PMID 33946243, 2021). "WFS1 mutations are also responsible for “uncommon” WFS1 phenotypes such as autosomal dominant low-frequency sensorineural hearing loss or an association between optic atrophy and deafness." (PMID 33946243, 2021). "The distribution of wolframin in the mammalian visual system, and the pathogenesis of optic atrophy due to mutations in WFS1 remain unclear." (PMID 20069065, 2010). "In one patient the diagnosis of an autosomal dominant Wolfram-like syndrome could be established, he carried a known pathogenic WFS1 variant, Ala684Val, which has been described in several families with autosomal dominant congenital HL and a later onset optic atrophy." (PMID 37108562, 2023). "WFS1 spectrum disorder (WFS1-SD) is a rare monogenic neurodegenerative disorder whose cardinal symptoms are childhood-onset diabetes mellitus, optic atrophy, deafness, diabetes insipidus, and neurological signs ranging from mild to severe." (PMID 37333802, 2023). "Classic WFS1-SD is an autosomal recessive progressive neurodegenerative disorder characterized by the onset of diabetes mellitus and optic atrophy before the age of 16 years." (PMID 37333802, 2023). "The reported yield of nuclear and mitochondrial DNA sequencing in bilateral optic atrophy is around 20% and includes pathogenic variants in the OPA1, mtDNA genes, or rarely WFS1, MFN2, POLG, ACO2, and DNAJC30 genes." (PMID 36294366, 2022).
optic atrophy (continued). "Mutations in WFS1 were primarily identified to cause Wolfram syndrome type 1 (WS1), a recessive condition characterized by diabetes, optic atrophy and deafness." (PMID 34867178, 2021). "Mutations in OPA1 and MFN2 genes cause autosomal dominant optic atrophy (DOA); mutations in WFS1 and CISD2 can cause Wolfram syndrome, while Leber's hereditary optic neuropathy (LHON) is associated with mutations in mitochondrial ND1, ND4, and ND6 genes." (PMID 32352005, 2020). "In the context of optic atrophy, several anatomical studies reported expression of WFS1 in optic nerve astrocytes, suggesting that failure of the surrounding glial cells has detrimental effects resulting in optic nerve degeneration." (PMID 29357349, 2018). "To WFS1-spectrum belongs also the autosomal dominant Wolfram-like syndrome, characterized by hearing loss and/or optic atrophy without the presence of all typical WFS-associated symptoms." (PMID 37108562, 2023). "The WFS1 gene was originally identified as the cause of Wolfram syndrome (MIM # 222300), which is an autosomal recessive disorder characterized by various symptoms including juvenile onset diabetes mellitus, optic atrophy, central diabetes insipidus, psychiatric disease, and hearing impairment." (PMID 39858604, 2025). "In addition, the WFS1 gene, responsible for Wolfram syndrome, is also responsible for DOA associated with neuro-sensorial deafness and for isolated recessive isolated optic atrophy." (PMID 35885985, 2022). "However, mutations in WFS1 are recognized as a frequent cause of optic atrophy independent of other WS1 symptoms." (PMID 34867178, 2021). "More recently, lamination of the outer plexiform layer has been observed in patients with optic atrophy caused by dominant, but not recessive, WFS1 mutations, and this peculiar OCT characteristic could be due to Müller cell dysfunction and disturbed calcium homoeostasis." (PMID 27696015, 2016). "In total, 116 patients with suspected optic neuropathy were examined, and 25 cases of LHON were diagnosed.The diagnostic rate for LHON of the Part A was 21.6% in our optic atrophy group using the mtDNA Sanger sequencing panel (OPA1, WFS1, etc., not included)." (PMID 33781268, 2021). "Bi-allelic mutations in the wolframin gene (WFS1) cause Wolfram syndrome 1 (WS1 or DIDMOAD) characterized by non-autoimmune diabetes mellitus, optic atrophy, diabetes insipidus, sensorineural deafness, urinary tract abnormalities, and neuropsychiatric disorders." (PMID 32938580, 2021).